MMP9 (matrix metallopeptidase 9)
Diseases named in the same sentence as MMP9 in open-access papers (continued):
Sharing a sentence is not in itself a finding about the gene and the disease.
pulmonary fibrosis (continued). "Here, we made a first contribution to evaluate the roles of MMP-2 and MMP-9 in a well-defined model of lung fibrosis using single and double KO mice lacking MMP-2 and -9, thereby establishing experimental conditions where lack of one gelatinase cannot be compensated by the other gelatinase." (PMID 35804363, 2022). "However, we found that neither MMP-2 or MMP-9 nor combined MMP-2/-9 deletion had any effect on experimental lung fibrosis in mice." (PMID 35804363, 2022). "It has been reported that an imbalance between MMP9 and TIMP1 plays a pivotal role in the pathogenesis of ARDS mainly through participating in airway remodeling, thus indicating the function of the MMP9/TIMP1 ratio in the evolution of pulmonary fibrosis in ARDS." (PMID 32969837, 2020). "Increases in the expression of MMP-9, which is also known as gelatinse A, may lead to degradation of all the components of the extracellular matrix and numerous non-matrix proteins in pulmonary fibrosis." (PMID 29311918, 2017). "For the pulmonary fibrosis evaluation, the fibrosis index calculated based on MT staining, collagen deposition and active TGF-β1 expression detected by ELISA, and the expression of TGF-β1, α-smooth muscle actin (SMA), fibronectin, MMP-9, and TIMP-1 by western blotting." (PMID 29311918, 2017). "In contrast, no significantassociations could be established with age (continuous), MMP-9 (continuous), SSctype (diffuse, limited), or presence of lung fibrosis (no, yes) in our SSc patient cohort." (PMID 19190762, 2008). "Moreover, MMP-9 depletion in KO mice does not substantially alter the extent of either pulmonary fibrosis or lung inflammation after bleomycin administration." (PMID 15663794, 2005). "Therefore, in the future, modification of R1R2 peptide, which can bind to MMP-9, but not to FN, may provide a superior therapeutic option for attenuating pulmonary fibrosis." (PMID 28968441, 2017). "We also found elevated levels of MMP-2 and MMP-9 protein in lung tissue of both patients with IPF and non-IPF lung fibrosis with UIP pattern, consistent with previous reports." (PMID 35804363, 2022). "Moreover, increased MMP-9 expression preceded increased TIMP-1 expression, the former peaking on day 3, and the latter peaking on day 7, a pattern that supports the notion an imbalance between matrix degradation and its inhibition may contribute to PQ-induced pulmonary fibrosis." (PMID 25945502, 2015).
emphysema (140 papers, 2003 to 2025). "Alveolar macrophages were the primary source of MMP-9 in the lungs of patients with emphysema, and its overproduction led to the loss of alveolar elastin and irreversible alveolar destruction." (PMID 40422181, 2025). "Elevated levels of matrix metalloproteinase-9 (MMP-9) and an increased MMP-9/TIMP-1 ratio are consistently associated with emphysema severity and extracellular matrix degradation in COPD." (PMID 41373549, 2025). "MMP9 encodes the enzyme Matrix metalloproteinase-9 (MMP-9) which is implicated in the development of emphysema, mediating inflammation through extracellular matrix degradation and neutrophil recruitment." (PMID 40894069, 2025). "More broadly, we believe this study connects to our prior work demonstrating that HIV increases oxidative stress in the alveolar space and that oxidative stress increases MMP-9 activity to provide a compelling overarching narrative of HIV-associated emphysema." (PMID 36331810, 2023). "Among other tissue-degrading proteases, MMP-9 and neutrophil elastase have been implicated in airway remodelling and emphysema development during COPD." (PMID 35676684, 2022). "AHR is mediated mostly by increased IFN-γ and RANTES concentrations, while the risk of emphysema was related to the activation of the IL-17 → MCP-1 → MMP-9 → MMP-12 axis." (PMID 36293561, 2022). "Intriguingly, elevated levels of MMP9 in sputum and plasma caused emphysema, as well as diminished FEV1, carbon monoxide transfer factor, and oxygen saturation in COPD exacerbation in patients exposed to CS." (PMID 34945480, 2021). "Increased AM and ELF MMP-1 and MMP-9 expression have been linked to emphysema in humans and in animal models." (PMID 27446965, 2016). "We have previously reported MMP-3, -7 and -10 were associated with overall quantitative measures of emphysema while Chaudhuri found MMP-9 and -12 were associated with this measure." (PMID 27460105, 2016). "For example, neutrophils release proteases such as neutrophil elastase (NE) and matrix metalloproteinase-9 (MMP-9) which cause tissue destruction resulting in emphysema." (PMID 27184092, 2016). "Clinical studies have implied that, among the biomarkers associated with emphysema, matrix metalloproteinase 9 (MMP-9) is of particular importance." (PMID 25635861, 2015). "Increased plasma MMP-9 levels are proposed to predict the decline of lung function as well as greater COPD exacerbations in A1AT deficiency-associated emphysema." (PMID 25635861, 2015). "Sputum MMP-9 concentrations in COPD are directly associated with the extent of emphysema measured by CT and MMP-9 expression levels are inversely associated with DLco." (PMID 27234393, 2013). "In contrast, Atkinson and colleagues have shown that the MMP-9 deficient mouse still develops smoke-induced emphysema." (PMID 23450717, 2013). "Our laboratory has demonstrated that the transgenic overexpression of MMP-9 in macrophages causes spontaneous adult-onset emphysema due to elastin degradation." (PMID 23450717, 2013). "In conclusion, disease severity in COPD when assessed by the extent of emphysema measured by CT is directly associated with sputum MMP-9 concentrations." (PMID 27234393, 2013). "The TGFB1 rs2241718 and MMP9 rs3918242 SNPs were associated with centrilobular emphysema (p = 0.022 and p = 0.008), and the TNF rs1800629 SNP with paraseptal emphysema (p = 0.017)." (PMID 23734748, 2013). "The TGFB1 rs2241718 and MMP9 rs3918242 SNPs were associated with centrilobular emphysema (p = 0.022 and p = 0.008, respectively), and the TNF rs1800629 SNP was associated with paraseptal emphysema (p = 0.017)." (PMID 23734748, 2013). "Together with the MMP9 rs3918242 variant T-allele the TGFB1 rs2241718 variant A-allele reduced the risk of pathological centrilobular emphysema into fifth compared to the wild-type genotype." (PMID 23734748, 2013). "We found a significant association between MMP9 rs3918242 variant T-allele and a lowered proneness to centrilobular emphysema." (PMID 23734748, 2013).
emphysema (continued). "MMP-9 induction was previously associated with the development of emphysema in lungs exposed to LPS." (PMID 22412999, 2012). "Among patients with AATD-associated emphysema, our data show that higher plasma MMP-9 levels were generally associated, both cross-sectionally and longitudinally, with poorer and declining pulmonary status, across multiple endpoints." (PMID 21429222, 2011). "A MMP9 promoter SNP has been associated with emphysema in a case-control study in a Japanese population." (PMID 21524282, 2011). "The increased expression of MMP-9 elevated the risk of cigarette smoke-induced emphysema." (PMID 40422181, 2025). "Matrix metalloproteinase 9 (MMP-9) is a lung tissue remodeling enzyme associated with emphysema." (PMID 36331810, 2023). "We hypothesized that HIV proteins would increase the risk of cigarette smoke-induced emphysema due to MMP-9." (PMID 36331810, 2023). "In addition, we studied the preventive effects of CIE on CSC-induced emphysema progression in vivo and in vitro, focusing on MMP-9 associated pathways." (PMID 36678124, 2023). "Additionally, cadmium has a direct impact on the adherence junction proteins, causing the synthesis of pulmonary MMP-2 and MMP-9, and accelerating collagen and elastin breakdown that results in emphysema." (PMID 37749472, 2023). "MMP-2 and MMP-9 have already been implicated in the pathogenesis of emphysema, so they may be potential therapeutic targets in the emphysema phenotype of COPD." (PMID 33535173, 2021). "MMP-9 −1562 C/T SNP, located on 20q11.2-q13.1 chromosome, has been under investigation for its association with an increased risk for the development of cancer and emphysema as well as many other diseases." (PMID 27194818, 2016). "Therefore, MMP-9 and TIMPs seem to be associated with airway obstruction while TIMPs are potentially related to tissue destruction respectively emphysema." (PMID 26126526, 2015). "Omachi and co-authors suggested that MMP-9 may be a valuable biomarker for the progression of emphysema with A1AT deficiency." (PMID 25635861, 2015). "In contrast, the carriage of at least one TGFB1 rs2241712 variant A-allele was found to halve the risk for centrilobular emphysema (OR 0.53, 95% CI 0.30-0.90), as was also the carriage of at least one MMP9 rs3918242 variant T-allele (OR, 0.51 95% CI 0.30-0.86)." (PMID 23734748, 2013). "The magnitude of the prospective associations between MMP-9 and pulmonary status measurements was, in many cases, modest from a clinical perspective, but the time period examined was short relative to the multi-year timeframe over which emphysema progresses." (PMID 21429222, 2011). "Thus, our longitudinal findings with respect to lung density and TLco suggest that, in AATD-associated emphysema, further study of a direct involvement of MMP-9 in disease progression is warranted." (PMID 21429222, 2011). "Moreover, we carried out this longitudinal analysis of MMP-9 in a relatively large cohort of AATD-associated emphysema, a well defined phenotype that offers a particularly valuable model of COPD progression." (PMID 21429222, 2011). "In particular, MMP‐9 and IL‐6 may be the best targets for prospective studies since they have been closely linked to the pathogenesis of chronic obstructive pulmonary disease, emphysema, rheumatoid arthritis, and various cancers." (PMID 38353387, 2024). "However, on the basis of previous investigations, where specific genes (e.g., MMP-9) were found to associate with upper lung dominant emphysema, we believe that specific genes could be associated with susceptibility to homogeneous emphysema." (PMID 25409328, 2014). "In COPD, activation of the NF-κB pathway enhances the secretion of MMP-9 by pulmonary epithelial cells, leading to the degradation of alveolar elastic fibers and basement membranes, and ultimately contributing to emphysema." (PMID 41184265, 2025).
emphysema (continued). "Recent studies have shown that CS exposure leads to increased levels of MMP9 in the sputum and plasma of patients, resulting in the development of emphysema and decreased FEV1, carbon monoxide diffusion capacity, and oxygen saturation during COPD exacerbation." (PMID 38891820, 2024). "Our study demonstrates the therapeutic potential of deflamin to attenuate the development of pulmonary emphysema and peribronchial fibrosis in mice chronically exposed to ozone through interacting and regulating the catalytic activity of MMP-9." (PMID 38791100, 2024). "The mechanism of the emphysema is complex, and matrix metalloproteinases, particularly MMP-9 and MMP-12, are of interest; activation of the IL-17 → MCP-1(Ccl-2) → MMP-9 → MMP-12 axis appears to be critical for the formation of emphysema." (PMID 38892239, 2024). "In this study, we provide novel evidence that smoking increases susceptibility to HIV-associated emphysema and implicate the HIV-1 viral protein Tat and the host protein MMP-9 as key actors in the process." (PMID 36331810, 2023). "On the other hand, transgenic overexpression of MMP-9 in macrophages led to impulsive emphysema in mice." (PMID 36835197, 2023). "In rodent models, overexpression of TGF-β leads to pulmonary fibrosis, whereas mice deficient in TGF-β signal transmission spontaneously develop emphysema, likely through the upregulation of MMP-9." (PMID 37174678, 2023). "The MMP9-mediated degradation illustrates a mechanism by which extracellular matrix remodeling occurs during emphysema and COPD." (PMID 40809472, 2023). "Our present findings show that decreased CRBN contributes to the development of emphysema by increasing neutrophilic inflammation, oxidative damage, and proteinase (MMP9) expression." (PMID 36290703, 2022). "To further substantiate the differential roles of NE vs. MMP-9 in emphysema formation, we performed invasive lung function testing as a sensitive tool to compare the effects of genetic deletion of NE vs. MMP-9 on lung mechanics in βENaC-Tg mice." (PMID 36362203, 2022). "Increased endothelial monocyte-activating protein-II (EMAPII), MMP-9, and MMP-12 levels are the primary cause of the development of emphysema by Moraxella." (PMID 35740358, 2022). "To test the relative contribution of MMP-9 vs. NE in emphysema formation, we complemented our studies of distal airspace morphometry with invasive pulmonary function testing in βENaC-Tg mice lacking either MMP-9 (βENaC-Tg/Mmp9-/-) or NE (βENaC-Tg/NE-/-)." (PMID 36362203, 2022). "To determine if MMP-9 contributes to emphysema formation, we performed measurements of lung volume, mean linear intercepts (MLI) and destructive index (DI) in lung tissue sections of βENaC-Tg, βENaC-Tg/Mmp9-/- and littermate control mice." (PMID 36362203, 2022). "Neutrophil elastase (NE) was reported to induce the epithelial apoptosis and emphysema; meanwhile, excessive MMP-9 released by macrophage can result in permanent alveolar destruction." (PMID 33436065, 2021). "Human MMP-9 was shown to induce emphysema in a murine model, and MMP-9/TIMP-1 imbalance was observed in patients with COPD." (PMID 33992109, 2021). "The MMP-9 concentration and the MMP-9/TIMP-1 ratio were higher in patients with emphysema than in those with other phenotypes." (PMID 33419373, 2020). "Others have shown that treatment with olaparib (PARP1 inhibitor) ameliorated MMP2 and MMP9 expression in an elastase-induced mouse model of emphysema." (PMID 33172999, 2020). "A growing body of evidence indicates that MMP9 and MMP12, largely secreted from macrophages, are implicated in the breakdown of lung tissues in COPD and emphysema." (PMID 32973788, 2020). "Epithelial cells and macrophages release proteases, such as matrix metalloproteinase-9 (MMP-9), which contributes to elastin degradation and the development of emphysema." (PMID 33374938, 2020). "In our study, MMP-9 concentration and the MMP-9/TIMP-1 ratio were the best predictors of emphysema in COPD patients." (PMID 30781876, 2019).
emphysema (continued). "MMP-9 concentrations and the MMP-9/TIMP-1 ratio were higher in patients with emphysema than in other phenotypes (both p < 0.01)." (PMID 30781876, 2019). "MMP-9 concentration and the MMP-9/TIMP-1 ratio are the best predictors of emphysema in COPD patients." (PMID 30781876, 2019). "Human MMP-9 induced emphysema in a murine model, and an MMP-9/TIMP-1 imbalance was observed in COPD patients with exacerbations." (PMID 30606200, 2019). "MMP-9 concentration and the MMP-9/TIMP-1 ratio were the best predictors of emphysema in COPD patients." (PMID 30781876, 2019). "Matrix metalloprotease (MMP)-9 and tissue inhibitor of metalloproteinase-1 (TIMP-1) which were reported to be associated with arterial stiffness were higher in patients with emphysema and COPD." (PMID 29783975, 2018). "A relationship between MMP9 concentration and pulmonary function, bronchodilator response, and emphysema severity has previously been suggested." (PMID 29760600, 2018). "In conclusion, the present study demonstrates that Gal-9 prevents PPE-induced inflammation and emphysema in mice by inhibiting the infiltration of neutrophils, leading to reduced MMP-9 production." (PMID 28704475, 2017). "Increased MMP-9 activity can augment the degradation of alveolar wall basement membranes, which results in the development of emphysema and airway fibrosis." (PMID 28831024, 2017). "In the present study, exogenous administration of Gal-9 in an emphysema animal model reduced the levels of MMP-9, MMP-2 and TIMP-1 in BALF, and these MMPs levels correlated significantly with the number of neutrophils in BALF." (PMID 28704475, 2017). "We found that Gal-9 attenuated PPE-induced emphysema in a murine model by inhibiting the infiltration of neutrophils and MMP-9 production in the lung." (PMID 28704475, 2017). "In support of this concept, intranasal administration of IL-23 protein to mice resulted in increased lung MMP-9, a protease linked to the influx of inflammatory cells into the lung in COPD as well as the destruction of lung tissue in emphysema." (PMID 27446965, 2016). "In mice, IL-17 is essential for the development of emphysema from long term CS exposure by activating the IL-17 → Ccl-2 → MMP-9 → MMP-12 signaling axis." (PMID 27363862, 2016). "Previous studies have shown that IL-17, an important mediator of CS-induced emphysema, induces the expression of inflammatory cytokines and matrix degrading proteinases MMP-9 and MMP-12." (PMID 27363862, 2016). "MMP-9 polymorphisms have been associated with CLE, but ours is the first study evaluating the contribution of MMPs to different emphysema sub-types in detail." (PMID 27460105, 2016). "MMP-9 activity is increased in the lung parenchyma of patients with emphysema, and correlated with FEV1." (PMID 26126526, 2015). "MMP-9, produced by the activated macrophages, has the ability to cleave elastin with a majority of emphysema progressive." (PMID 26646821, 2015). "Our lab established a role for MMP-9 expression in the progression of lung degradation and the development of emphysema by expressing human MMP-9 in the macrophages of transgenic mice." (PMID 25664615, 2015). "Since TNF-α and MMP-9 play important roles in the pathogenesis of emphysema, we examined their expressions in lung tissue." (PMID 26646821, 2015). "In particular, polymorphisms in MMP9 and TGFB1 are proposed to protect against centrilobular emphysema, and polymorphisms in TIMP2 and TNF seem to increase the risk for paraseptal emphysema and/or airflow obstruction." (PMID 23734748, 2013). "Nevertheless circulating monocytes from subjects with advanced emphysema on computed tomography (CT) produced more MMP-9 than controls." (PMID 27234393, 2013). "The extent of emphysema (% LAA −950) was significantly associated with sputum MMP-9 protein concentration [r = 0.442 (0.171, 0.634), p = 0.020,)] and MMP-9 activity [r = 0.447 (0.219, 0.643), p = 0.010]." (PMID 27234393, 2013).